FMR1 (fragile X messenger ribonucleoprotein 1)
Diseases named in the same sentence as FMR1 in open-access papers (continued):
Sharing a sentence is not in itself a finding about the gene and the disease.
Anxiety (continued). "The findings reviewed in this article suggest that CBD may have anxiolytic effects not dependent on the Fmr1 gene, which is mutated in FXS, characterized by signs such as anxiety and motor hyperactivity." (PMID 35629320, 2022). "Additionally, perinatal exposure to the Control Fat diet (similar to a “Western” diet) further diminished nonsocial anxiety in the Fmr1 knockout." (PMID 35089938, 2022). "The vehicle injected Fmr1‐KO mice showed an increase of time spent and in number of entries in the open arms of the elevated plus maze (EPM) compared to the WT‐vehicle mice (1.9‐ and 1.8‐fold of mean increase, respectively), suggesting a decreased anxiety induced by the genotype." (PMID 35373916, 2022). "Neither male nor female Fmr1 KO mice exhibited a change in anxiety compared to that of WT mice." (PMID 36688132, 2022). "Selective deletion of Fmr1 from forebrain excitatory neurons induces cellular, electrophysiological, and behavioral phenotypes in mice including increased mTOR/Akt phosphorylation and enhanced locomotor activity, but not anxiety-like behavior." (PMID 35768828, 2022). "Interestingly, hyperactive locomotor behavior, but no changes in anxiety-like behaviors, was observed in mice with forebrain excitatory-specific Fmr1 deletion, pointing to combined cortical and subcortical contributions to behavioral deficits in FXS." (PMID 34690832, 2021). "Our results suggest that low-dose BAER-101 may be beneficial to normalize circuit hyperexcitability and improve object recognition memory but did not improve anxiety- and repetitive behavior-related phenotypes in Fmr1 KO mice." (PMID 34093287, 2021). "Interestingly, several behavioral phenotypes, such as hyperactivity of Fxr2 KO and Fmr1 KO mice and anxiety of Fmr1 KO mice were not replicated across studies." (PMID 30087606, 2018). "The phenotype we observed in 0.25 mg/ml, but not in 1 mg/ml, could account for increased anxiety or hyperactivity in Fmr1 KO mice, provoked by baclofen treatment in a dose that does not sedate the animals as a side effect." (PMID 29785777, 2018). "Main effects of genotype and treatment approached statistical significance suggesting that anxiety may be lower in Fmr1 KO mice regardless of treatment and that in both genotypes, rapamycin treatment tended to increase anxiety-like behavior." (PMID 29375310, 2017). "Entering the open arms of the plus maze at control levels may reflect Fmr1 KO mice moving more vigorously within the maze rather than any anomaly in the anxiety the mouse experiences." (PMID 24550778, 2014). "Thus, Fmr1-KO mice exhibited hyperactivity in response to novel environments, which normalizes with repeated exposure and familiarization, in the absence of anxiety-related behavior." (PMID 24312033, 2013). "Quantitative reverse transcription assays (qRT-PCR) estimate the FMR1 expression levels to evaluate the full clinical spectrum and resolve the dilemma of overlapped clinical features of PM carriers that could be common with FM cases as ADHD, ASD, depression, and anxiety." (PMID 36409419, 2023). "Deletion of Fmr1 in PV+, but not somatostatin-positive (SST+) neurons, resulted in abnormal anxiety and social behaviors, and dysregulated de novo protein synthesis." (PMID 41469555, 2025). "We found that cell type-specific deletion of Fmr1 in PV, but not SOM-expressing neurons, results in behavioral alterations, including anxiety-like behavior and deficits in social interaction." (PMID 35768828, 2022). "Additionally, Fmr1 KO mice performed similarly to their WT littermates in Y maze, open field test, elevated plus maze and novel object recognition test, indicating that their working memory, locomotion, non-social anxiety levels and hippocampus-independent recognition memory are all normal." (PMID 33215988, 2020). "Indeed, disturbances in social recognition and interaction, non-social anxiety, and spatial memory were corrected by BMS-204352 in Fmr1 KO mice." (PMID 25079250, 2014).
Cognitive impairment (97 papers, 2011 to 2026). Abnormal cognition is characterized by deficits in thinking, reasoning, or remembering. "Collectively, Rilmenidine corrected abnormalities in spine density/structure and cognitive deficits associated with Fmr1 KO mice." (PMID 40931164, 2026). "Loss of FMR1 function leads to characteristic neurological and cognitive deficits, with additional contributions from impaired FMR1-RNA interactions." (PMID 40588021, 2025). "We found that transient treatment with Nutlin-3 of 2-month-old young adult FMR1-deficient mice prevents the emergence of neurogenic and cognitive deficits in mature adult FXS mice at 6 months of age." (PMID 35549943, 2022). "Since FXS is an X-linked disorder caused by a trinucleotide repeat expansion in the FMR1 gene, most females have both a functional and a silenced copy of the FMR1 gene, resulting in a less severe degree of cognitive impairment compared to males." (PMID 34733188, 2021). "A FXS mouse model with constitutive deletion of the Fmr1 gene (Fmr1 KO) has been used extensively to study neural mechanisms underlying cognitive impairments of FXS patients." (PMID 33215988, 2020). "Studies of FMR1 alleles have shown that the methylation of specific sites is predictive of intellectual impairment in full mutation females." (PMID 25348928, 2014). "A previous study reported enhanced psychomotor speed, and subtle but significant cognitive impairments, modulated by age and by mutations in the fragile X mental retardation 1 (FMR1) gene in adult female fragile X premutation carriers (fXPCs)." (PMID 23148490, 2012). "On the other hand, the decrease in the hippocampal GluN2B levels may be linked to aberrant induction of LTD in Fmr1 KO rats, which could potentially explain the cognitive deficits observed as well." (PMID 38378836, 2024). "In addition to intellectual impairment, FMR1 gene mutations are also associated with reproductive disorders, such as early menopause in females, and macroorchidism in males." (PMID 36909303, 2023). "Like FXS in humans, loss of Fmr1 in rodents also cause sensory, behavioral, and cognitive deficits." (PMID 34714519, 2022). "This could potentially contribute to cognitive impairment or other phenotypes of Fragile X syndrome, a disorder caused by trinucleotide repeat expansions in the FMR1 gene that leads to loss of FMRP." (PMID 34434089, 2021). "Impaired novel object recognition in Fmr1 KO mice was observed by others and may reflect cognitive deficits associated with FXS." (PMID 34093287, 2021). "Using Fmr1 knockout (Fmr1 KO) mice, we and others have demonstrated that the cognitive impairments in FXS may be linked to a disruption in N-methyl-D-aspartate receptor (NMDAR)-dependent synaptic plasticity in the hippocampal dentate gyrus (DG)." (PMID 30705620, 2018). "In summary, our study identified a new role of autophagy in actin assembly, spinemorphology, and cognitive deficits in Fmr1 KO mice." (PMID 40909783, 2025). "Long‐term (13‐week) administration significantly improves autistic phenotype and cognitive deficits in Fmr1 KO2 mice; short‐term treatment is ineffective." (PMID 41244006, 2025). "Our findings demonstrate that the transplanted MGE cells successfully migrated within the hippocampus, differentiated into INs, and ameliorated cognitive deficits in Fmr1‐KO mice." (PMID 39823534, 2025). "Contrary to this, monotherapy ibudilast (BID or QD) was able to completely reverse the cognitive deficit in Fmr1 KO mouse as measured in the NOL, OL and SR assays, back to levels observed in the WT animals." (PMID 38226317, 2024). "Present findings provide evidence linking Fmr1 deletion with cognitive deficits that arise, at least partly, from perturbations of glutamatergic and GABAergic neurotransmission, apparent at the transcription, protein and synaptic level." (PMID 38378836, 2024).
Cognitive impairment (continued). "Ibudilast treatment was however able to reverse this cognitive deficit dose dependently, with the 6 mg/kg group improving the D2 score in Fmr1 KO mice." (PMID 38226317, 2024). "Much of ibudilast’s efficacy is targeted towards reversing the cognitive deficits in Fmr1 KO mice, particularly for the BID group where cognition was improved for all the cognitive assays tested: NOR, OL, SR and cFC." (PMID 38226317, 2024). "Fmr1 KO rats exhibit hyperactivity, cognitive impairment, glutamatergic and synaptic plasticity dysregulations." (PMID 38378836, 2024). "While both chronic and acute administration of rimonabant, the CB1R antagonist, improved cognitive impairment, only acute administration led to improved pain desensitization in Fmr1 KOs." (PMID 37671673, 2023). "Pharmacological inhibition of PDE2A normalized the communicative (p < 0.01, p < 0.05), social (p < 0.001, p < 0.05), and cognitive impairment (p < 0.001) displayed by both Fmr1-Δexon 8 and VPA-exposed rats." (PMID 35338117, 2022). "These interactions are disrupted in Fmr1-KO mice and upregulation of Homer1a expression rescued cognitive deficits." (PMID 34440392, 2021). "In light of previous findings on object-recognition impairment mediated by aberrant DA release in Fmr1-KO mice, our results indicate intranasal application of DA is an effective avenue for ameliorating the cognitive deficits in the FXS model." (PMID 32778145, 2020). "They concluded lower FMR1 mRNA and FMRP levels were the main contributors to cognitive impairment and the presence of a normal allele appeared to compensate in some but not all individuals." (PMID 33008014, 2020). "Rat models of FXS include the FMR1-knockout (FMR1-KO) mice, which show cognitive deficits, abnormal immature neuronal morphology, and lack the normal fragile X mental retardation protein (FMRP), that is important for normal cognitive development." (PMID 30894830, 2019). "Here we explored the dynamics of mGluR5 at hippocampal synapses and the consequences of a disrupted interaction with Homer proteins for NMDAR function and plasticity, as well as for related cognitive deficits in Fmr1 KO mice." (PMID 29062097, 2017). "Strong cognitive deficits in an Fmr1 mouse model in a task with face validity to touchscreen methods used in humans with FXS would offer a novel preclinical research tool to test compounds for therapeutic efficacy." (PMID 27022628, 2016). "Surprisingly, cognitive deficits in Fmr1 mice have proven remarkably mild and somewhat inconsistent across publications." (PMID 27022628, 2016). "Specifically, this rearing condition rescued Fmr1-KO adult mice deficits, namely, hyperactivity, social interactions, and cognitive deficits." (PMID 27274875, 2016). "CTEP, a newer anti-mGluR5 inhibitor that is more potent and long lasting than MPEP, has been shown to correct for audiogenic seizures, hippocampal long-term depression, and cognitive deficits in Fmr1 KO mice." (PMID 23803181, 2013). "Patients with FXS exhibit cognitive deficits and Fmr1 KO mice display deficits in visual memory." (PMID 40931164, 2026). "5-HT7 agonists rescued synaptic plasticity, learning deficit and stereotyped behavior in Fmr1 KO mice, and therefore might be proposed to treat Fragile X patients with cognitive impairment and autistic features." (PMID 40141138, 2025). "On this basis, it was decided to test the efficacy of gaboxadol and ibudilast in combination and to assess whether the co-treatment of these drugs could improve the cognitive deficits as well as the behavioural phenotypes in Fmr1 KO mice." (PMID 38226317, 2024). "We report three patients with an unmethylated FM FMR1 alleles without any behavioral or cognitive deficits." (PMID 38540390, 2024). "Several studies have shown that Fmr1-KO mice display cognitive impairments." (PMID 35338117, 2022).
Cognitive impairment (continued). "Since our current study has revealed a persistent therapeutic effect of Nutlin-3 on impaired NSC activation and neurogenesis in Fmr1 KO mice, we decided to investigate whether the Nutlin-3-dependent restoration of cognitive deficit is also long-lasting." (PMID 35549943, 2022). "Given that seizures during early life can result in long-lasting cognitive impairments in Fmr1 KO mice, gerbil models of FXS have a high potential to help understand seizure generation in FXS children and further assess the impact of seizures on other cognitive and behavioral phenotypes of FXS." (PMID 35626665, 2022). "Treatment of Fmr1-KO mice with Bay 60–7550 normalizes the social and cognitive deficits of infant and adolescent Fmr1-KO mice, increased the maturity of axons and dendritic spines of Fmr1-KO neurons and normalizes the exaggerated hippocampal m-GluR5 long-term depression of Fmr1-KO CA1." (PMID 33414502, 2021). "Cognitive deficit has been extensively validated in Fmr1 KO mice." (PMID 33215988, 2020). "Additionally, social enrichment early in life (birth to weaning) has been found to rescue hyperactivity and social and cognitive deficits in FMR1-KO mice, as well as neural morphology into adulthood, with no similar effects seen in wild-type controls." (PMID 30894830, 2019). "In this perspective, in this manuscript we also investigated whether systemic administration of LP-211 to Fmr1 KO might rescue learning and behavioral deficits that mirror cognitive impairment and autistic-like behavior in FXS patients." (PMID 30333723, 2018). "The existence of these mosaic cases reveals that genetic variations in FMR1 gene, that affect FMRP expression levels, may underlie cognitive impairment in similar neurodevelopmental disorders." (PMID 30450110, 2018). "Importantly, we found that restoring this mGluR5/Homer interaction by reducing the expression of Homer1a in the hippocampus rescued abnormal NMDAR function and plasticity as well as cognitive deficits in Fmr1 KO mice." (PMID 29062097, 2017). "However, given the primary symptom of intellectual disability in humans with FXS, cognitive deficits in Fmr1 KO mice were expected to be robust enough to withstand some variability in methods, background genetics, and environmental issues." (PMID 27022628, 2016). "Our study also reveals that rimonabant doses can be reduced further by administering the drug every two days to obtain the same amelioration on the memory deficit present in the Fmr1 KO mice, and an even lower dose of rimonabant (0.03 mg/kg) also improved the cognitive deficit." (PMID 27589806, 2016). "Here we developed a delayed nonmatching to position touchscreen task to test the hypothesis that paradigms placing demands on working memory would reveal robust and replicable cognitive deficits in the Fmr1 KO mouse." (PMID 27022628, 2016). "It remains possible that our tasks, while designed to challenge working memory capacity, may have been insufficiently difficult to reveal cognitive deficits in Fmr1 mice." (PMID 27022628, 2016). "Because of these diverse findings, we sought to develop more sensitive touchscreen tasks to detect robust cognitive deficits in Fmr1 mice on the FVB/AntJ background, which could be used in preclinical discovery of therapeutics." (PMID 27022628, 2016). "It is characterized by cognitive impairment and physical and behavioral problems and is caused by the silencing of fmr1 transcription and the absence of the fmr1 protein (FMRP)." (PMID 23536755, 2013). "The pathological outcomes of this ramRNA-mediated FMR1 gene silencing were corresponded to the neurodegenerative and cognitive impairments in FXS disorders, like neuronal deformity, immature synapse formation, long dendritic spine shaping, LTP diminishment, and mGluR-LTD augment." (PMID 22779005, 2012). "Additionally, the C-terminal fragment alleviated locomotion and cognitive deficits in Fmr1 KO mice." (PMID 40480633, 2025).
Cognitive impairment (continued). "Importantly, we demonstrate that ibudilast and gaboxadol co-treatment was able to rescue more phenotypes, including behaviours and cognitive deficits, in Fmr1 KO mice than either drug could achieve as monotherapies." (PMID 38226317, 2024). "Thus, the probabilistic learning and reversal learning tests may produce a more robust phenotype in Fmr1-KO mice that can advance understanding and treating cognitive deficits in FXS." (PMID 36688132, 2022). "Similarly, the Fmr1 KO2 mouse model was characterized by disruption of hippocampal neurogenesis, synaptic plasticity and neuronal communication, thus reflecting a possible mechanism underlying the cognitive impairments in FXS and similar autistic conditions." (PMID 34121987, 2021). "Notably, 0.05 mg/kg trifluoperazine rescued the cognitive impairment in Fmr1 KO mice." (PMID 32179850, 2020). "Most of the FXS research in mammalian model systems is limited to two disease models, the Fmr1 KO mouse and Fmr1 KO drosophila animal model, but the central issue in using these models is variability and small effect size of the phenotype particularly in the area of cognitive defects." (PMID 31035599, 2019). "Previous studies using Fmr1 knockout (Fmr1 KO) mice have suggested that a N-methyl-D-aspartate receptors (NMDAR) hypofunction in the hippocampal dentate gyrus may partly contribute to cognitive impairments in FXS." (PMID 30705620, 2018). "In the FXS mouse model, ICAM5 expression is aberrantly increased, correlated with the developmental delay of spine maturation and the concomitant cognitive impairment, and the reduction of ICAM5 expression rescues the behavioral disorders in Fmr1 KO mice." (PMID 31882402, 2020). "Fmr1 mutant mice show enhanced protein synthesis-dependent mGluR-mediated LTD and dendritic spine elongation, together with cognitive deficits, social anxiety and impaired social interaction." (PMID 23935565, 2013). "Consistent with this, cognitive impairments of the two animal models are corrected by drugs that modulate mGluR5 in the opposite manner (CDPPB for Tsc2+/− mice and MPEP for Fmr1−/y mice)." (PMID 23935565, 2013). "FXTAS is a neurodegenerative disorder occurring in some Fragile X Messenger Ribonucleoprotein 1 (FMR1) gene premutation carriers (PMCs) and is characterized by cerebellar ataxia, tremor, and cognitive deficits that negatively impact balance and gait and increase fall risk." (PMID 38676203, 2024). "Patient P-5 is a 66-year-old female, carrying 56 GGC repeats in the FMR1 gene and has been experiencing upper limb tremors for eleven years with no signs of ataxia, cognitive impairment or autonomic dysfunction." (PMID 38961870, 2024). "Neither acute nor chronic doses of gaboxadol were able to reverse the cognitive deficit in Fmr1 KO mice for the NOR task or the object location (OL) assay." (PMID 38226317, 2024). "In contrast to our hypothesis of a higher vulnerability of the Fmr1 mutant genotype, the FXS-like behavioral phenotypes of the HET females, i.e., hyperactivity and cognitive deficits, were unaltered by stress, independently of maternal experience." (PMID 37511156, 2023). "Genetic ICAM5 intervention attenuated behavioral deficits in Fmr1 KO mice, which may provide therapeutic benefits in the treatment of FXS cognitive impairment and other NDDs." (PMID 31882402, 2020). "This adds to a large body of behavioural data on the fmr1 ko mouse in which either no cognitive impairments, or relatively mild or inconsistent (across strains and testing protocols) impairments have been reported." (PMID 27022628, 2016). "To test whether bilateral delivery of Kir4.1-GFP into hippocampal astrocytes can rescue cognitive impairment in Fmr1 KO male mice, we employed the novel object recognition (NOR) test." (PMID 38678030, 2024).